TNF (tumor necrosis factor)
Diseases named in the same sentence as TNF in open-access papers (continued):
Sharing a sentence is not in itself a finding about the gene and the disease.
psychiatric disorder (continued). "Genes of pro-inflammatory cytokines IL-1β, IL-6, and TNF were significantly upregulated in MSB macaques, which was similar to results from human psychiatric disorder studies." (PMID 34394017, 2021). "Therefore, the influence of psychiatric disorders in a portion of the subjects may be minimal for apoE2/3/4 and TNF‐α proteins, although a possibility remains that psychiatric disorder or medication in these subjects contributed to negative results in other proteins." (PMID 32426945, 2020). "Although some studies have found MCP-1 to be lower in patients with MDD, our findings of higher levels of TNF-α and MCP-1 in the patient group add to several studies showing a correlation between psychiatric disorders and elevated pro-inflammatory cytokines." (PMID 29631540, 2018). "The activation of these innate immune mechanisms, including proinflammatory cytokines, such as IL-1, IL-6, TNF-α, and CRP, may contribute to the development of psychiatric disorders." (PMID 38742123, 2024). "C-reactive protein (CRP), tumor necrosis factor (TNF), soluble TNF receptor 1 (sTNFR1) and interleukin-6 (IL-6) are among the most frequently investigated inflammatory markers in the field of severe mental illness and exercise research." (PMID 37265560, 2023). "The vast majority of patients who experienced a manic/hypomanic episode (93.2%) had no history of psychiatric disorders until exposure to TNF‐α inhibitors." (PMID 34590391, 2022). "This study also replicates and extends the literature on the relationship between neuroticism, the L/A ratio, adiponectin, CRP, IL-6 and TNF-α by focusing on previously unaddressed populations: young adults with and without psychiatric disorders." (PMID 33963214, 2021). "Inflammatory cytokines or other inflammatory stimuli (e.g., IL-1β, IL-4, IL-6, TNF-α, and MCP-1) induce depressive symptoms or other psychiatric disorders, and these factors may also predict the development of these disorders." (PMID 33536923, 2020). "Moreover, our study included inflammatory markers that are not usually studied, including IL-1β, TNF-alpha and adiponectin, while controlling for health risk-related behaviors (including physical inactivity) and performing a systematic assessment of comorbid psychiatric disorders." (PMID 31798472, 2019). "However, the effect of psychiatric disorders on non-compliance to IBD treatment has been observed not only with anti-TNF agents, but also with aminosalicylates and immunomodulators." (PMID 33498197, 2021). "Because neuroinflammation occurs in many neurological and psychiatric disorders in the absence of a diagnosed inflammatory condition, TNFα inhibitors may also prove efficacious in patients without an underlying autoinflammatory disease." (PMID 34511110, 2021). "The proportion of patients with any psychiatric disorders did not moderate the associations between childhood trauma and CRP (t=0.02, P=0.98, I2res=74.0%, τ2=0.007), IL-6 (t=0.23, P=0.82, I2res=48.5%, τ2=0.006) or TNF-α (t=0.54, P=0.61, I2res=42.7%, τ2=0.01)." (PMID 26033244, 2016). "Recently published systematic review and meta-analysis evaluated the peripheral levels of pro-inflammatory markers including IL-1β, IL-6, TNF-α, and CRP between the elderly with AD and controls without any psychiatric disorder." (PMID 31277647, 2019).
heart disease (97 papers, 2007 to 2025). "TNF-α and its receptors have both pathogenic and cardioprotective roles in heart disease (Rolski and Błyszczuk, 2020)." (PMID 37081960, 2023). "TNF-α is a classical marker of chronic inflammatory processes and is associated with the development of heart disease in Chagas patients." (PMID 35720419, 2022). "Additionally, TNFα is implicated in angiogenesis and thrombogenesis, which are important in heart disease development." (PMID 38256155, 2024). "TNFα was one of the first pro-inflammatory cytokines linked to heart diseases." (PMID 38256155, 2024). "As TNF-α is cardiotoxic and can induce cardiac dysfunction, and production of TNF-α by transgenic cardiomyocytes was sufficient to cause severe heart disease, we hypothesized that ADAM17 may upregulate TRAF3 expression through TNF-α." (PMID 39406701, 2024). "The inflammatory response caused by heart disease is not limited to the myocardial tissue, and a large number of pro-inflammatory factors including IL-6, TNF-α, IL-1β, and monocyte chemoattractant protein-1 (MCP-1) also reach the brain through blood circulation." (PMID 38327496, 2024). "We also investigated whether IL-6 and TNF-α predict all-cause morbidity, cardiac disease, and all-cause mortality in gorillas and found that cardiac disease was best predicted by lower TNF-α alongside age and sex." (PMID 36230446, 2022). "Elevated serum levels of TNF-α are associated with progression of heart diseases, therefore, by reducing pro-inflammatory cytokines in the myocardium, MSCs may shift the microenvironment towards an anti-inflammatory profile." (PMID 33291410, 2020). "Lower EFs may be associated with increments of TNFα, which causes depressive moods; the level of TNFα may decrease after the treatment of heart disease, leading to an improvement in the mood." (PMID 33339355, 2020). "Increases in circulating TNF-α concentrations have been associated with heart disease progression." (PMID 18652680, 2008). "Also, cagA-induced inflammation may promote the release of cytokines (including IL-8), tumor necrosis factor- α (TNF-α), and T and B lymphocytes, thereby causing cardiac diseases." (PMID 40102932, 2025). "Thus, CCL20-induction by stimulation with TNF-α may be a good marker associated with heart diseases." (PMID 36012347, 2022). "In cardiac tissues, IL-17 induces the expression of diverse proinflammatory cytokines/chemokines and demonstrates strong synergic action with IL-1β and TNF-α to induce an inflammatory milieu that augments cardiac disease progression through different pathways." (PMID 40672362, 2025). "Future studies with a large sample size and involving markers of endocrine (aldosterone)-inflammation (TNF-α) markers in CHF developed due to ischaemic heart disease are required to explore the relationship." (PMID 36899939, 2023). "The severity of heart disease is also determined via the relationship between the circulating levels of TNF-α and functional HF classification." (PMID 36012347, 2022). "Several inflammatory cytokines, such as TNFα, the IL-1 family, IL-6, IL-8, IL-10, IL-18, and IFNα have also been shown to play a pathological role in various heart diseases." (PMID 35069538, 2021). "Pro-inflammatory cytokines such as TNF-α, IL-1β and IL-6 and inflammatory mediators like NF-kB were considerably boosted during the cardiac disease and similar momentum was observed in the disease control group mice." (PMID 32762480, 2020). "TNFα is an indicator of systemic inflammation and a poor prognostic factor in patients with heart disease." (PMID 32588117, 2020). "As proinflammatory/profibrotic mediators are also augmented in cardiac disease, the effect of a range of proteins, including Ang II, TGFβ1, IL-1β, IL-1α, TNFα, IL-6 and IL-6 in combination with the sIL-6R on Cx43 mRNA expression was examined in CFs." (PMID 31909243, 2020). "Altogether, these data indicate that global blocking of TNF is contraindicative for heart disease due to a protective role of TNFR2." (PMID 32528961, 2020).
heart disease (continued). "Anti-TNF-α therapy is widely used in treating autoimmune inflammatory disorders, but in case of patients with heart disease, this treatment was unsuccessful or even harmful." (PMID 33053859, 2020). "During the cardiac disease, increase the synthesis of cytokines especially TNF-α in the heart tissue by triggering the NF-kB." (PMID 32762480, 2020). "Taken together, these results demonstrate the presence of functionally significant interactions between RAS and TNF in the heart and suggest an important role for these interactions in the development of cardiac disease in this model." (PMID 23056347, 2012). "We analyzed PM effect on cytokine levels in 21 individuals with known cardiac disease by pairing 59 repeated-measures of endothelin-1, IL-6 and IL-6 receptor, TNF-α and TNF-α receptors [p55, p75], and MCP-1 to outdoor residence level measures of PM." (PMID 17270049, 2007). "The significantly increased EVs in the plasma of patients with heart disease may carry IL-1β and TNF-α and other pro-inflammatory cytokines transmit “danger or inflammatory signals” to other organs or cells, especially cardiomyocyte-derived EVs." (PMID 38327496, 2024). "Previous studies showed that certain biomarkers of inflammation are elevated during AMI, especially CRP and TNF-α, and the levels of CRP and TNF-α may determine the degree of myocardial damage and prognosis of heart disease." (PMID 35818572, 2022). "TNF⁃α is a proinflammatory cytokine, which increases in several cardiac diseases." (PMID 36059969, 2022). "Moreover, another research identified the down-regulation of IL-6 and TNF-α as a sign of amelioration of heart disease." (PMID 34526481, 2021). "For example, adiponectin, a fat-derived hormone, was demonstrated to stimulate AMPK and cyclooxygenase-2 activities, both of which could antagonize apoptosis and TNFα production, thereby suppressing tissue inflammation in heart diseases." (PMID 33639958, 2021). "Thus, patients receiving a dose of 100 × 106 allogeneic MSCs showed better outcomes in endothelial function and in the reduction of levels of the proinflammatory cytokine, tumor necrosis factor-alpha (TNF-α), usually increased in heart disease." (PMID 34683184, 2021). "Thin patients with heart disease have high tumor necrosis factor (TNF)α levels." (PMID 32588117, 2020). "In the light of these findings, it seems that targeting the TNF-α pathway in heart disease may show therapeutic benefits, but this approach must be more specific and selectively block pathogenic mechanisms." (PMID 33053859, 2020). "However, despite this success the development of serious side-effects and the failure of clinical trials in specific indications such as heart disease and MS revealed the limitations of anti-TNF therapy." (PMID 32528961, 2020). "Interestingly, the same study demonstrated that the fraction of antigen‐specific T cells measured by surface CD4+/CD154+ and intracellular CD4+/TNF‐α+ T cells was almost undetectable in chronic adult chagasic patients with mild cardiac disease." (PMID 28967229, 2018). "Previously, PTX was demonstrated to ameliorate cardiac dysfunction in patients with noninfectious heart disease in association with downmodulation of inflammatory biomarkers such as plasma TNF concentrations." (PMID 27161638, 2016). "Studies on the specific role of cytokines in the immune response against T. cruzi have been recently reported and demonstrate that large amounts of Th1 pro-inflammatory cytokines such as Interferon Gamma (IFN-γ), Tumor Necrosis Factor Alpha (TNF-α) are related to cardiac disease." (PMID 24608170, 2014). "For example, microRNA-21 (miR-21), an abundant microRNA whose primary transcript is upregulated by TNFα (Additional file1C), is upregulated in many types of heart disease and may be a useful therapeutic target." (PMID 24564208, 2014). "Finally, correlations of cytokine blood levels to heart disease can be misleading as exemplified by TNF." (PMID 23325387, 2013).
heart disease (continued). "Its client proteins have been found to be involved in cardiac disease pathways such as MAPK signaling, TNF-α signaling, etc." (PMID 38553458, 2024). "Numerous client proteins of HSP90 have been identified in known cardiac disease pathways, including MAPK signaling, PI3K/AKT (PKB)/mTOR, and TNF-α signaling, all of which are direct and indirect targets of HSP90." (PMID 36359837, 2022). "Numerous client proteins of HSP90 have been identified in known cardiac disease pathways, including MAPK signaling, PI3K/AKT (PKB)/mTOR, and TNF-α signaling." (PMID 36359837, 2022). "The results provide new insights to understand the mechanisms by which TNF-α stimulated VCAM-1 expression in HCFs associated with amplifying the inflammatory responses, supporting the hypothesis that TNF-α may play a key role in the exaggeration of cardiac diseases." (PMID 26858641, 2015). "Systemic inflammatory profile, enriched in NO and cytokines such as tumor necrosis factor (TNF) and interferon-gamma (IFNγ), is detected in CD patients and in experimental chronic T. cruzi infection related with the severity of cardiac disease." (PMID 41237192, 2025). "Our findings align with human trials that have not consistently shown improved cardiac outcomes from TNF-α inhibition, despite its link to animal models of heart disease." (PMID 41011058, 2025). "Corroborating previous data, the subgroup of CD patients with severe heart disease (C group) had increased TNF serum levels when compared to patients without heart disease (A group)." (PMID 39591456, 2024). "It has been shown that patients who present a mild heart disease or are in the indeterminate phase of CD produce high levels of IL-17 and IL-10 whereas patients with severe heart disease show high levels of IFN-γ and TNF-α." (PMID 35097133, 2022). "Survival was paralleled by reduced heart inflammation and tissue damage, without interference in parasite control, placing TNF as a key cytokine in the pathogenesis of T. cruzi-elicited cardiac disease." (PMID 35320825, 2022). "Several studies have also linked the expression of TNF-α or SDF-1 to many cardiac pathological conditions, however, a link between TNF-α, SDF-1 and their association with severity of alcohol mediated cardiac disease has not been explored." (PMID 29487525, 2018). "The main finding of this study is that sildenafil in human cardiomyocytes inhibited protein and gene expression of IFNγ + TNFα-induced chemokine CXCL10 (IC50 2.6 × 10−7 M), which is a critical trigger of early Th1 immune/inflammatory response during cardiac diseases." (PMID 27165639, 2016). "The development of drugs selectively targeting TNFRs, rather than blocking TNF-α activity, might represent a novel and more effective therapeutic concept in the treatment of heart disease." (PMID 33053859, 2020). "Several studies have shown a systemic increase in TNF-α+ monocytes, oxidative stress (e.g., lipid hydroperoxides), and an abundance of CD8+T cells that express inflammatory cytokines and cytotoxic molecules in Chagas patients with clinically symptomatic heart disease." (PMID 31905606, 2019). "The results provide new insights into the mechanisms of TNF-α action on HCFs to up-regulate the VCAM-1 expression and then amplified the inflammatory responses, supporting the hypothesis that TNF-α may play a key role in the development of cardiac diseases." (PMID 26173590, 2015). "Moreover, they had lower levels of lymphocyte count, albumin, EGFR, and TBIL, and higher levels of SBP, cardiac biomarkers (Hs-TnI, CK-MB, Myo, and NT-proBNP), WBC, neutrophil, inflammatory factors (Hs-CRP, IL-2R, IL-6, IL-8, and TNFα) and D-dimer in comparison to survivors without cardiac disease." (PMID 33553255, 2020).
heart disease (continued). "In noninfectious conditions, the participation of TNF in ischemic and dilated heart disorders is supported by several observations, including elevated plasma TNF levels, and raised the proposal of using TNF blocking as immunotherapeutic strategy for improving the severity of heart diseases." (PMID 25140115, 2014). "Other cytokines (TNF-alpha, IL-4, IL-17, IFN-gamma, CCL2, and IL-10) have shown differences between severe chagasic heart disease and the undetermined stage but not between the different stages of chagasic heart disease progression." (PMID 32455143, 2020). "Furthermore, TNF itself may trigger and/or maintain the nonbeneficial systemic inflammatory profile and the detrimental cardiac inflammation, which may crucially contribute to the pathogenesis of the heart disease in chronic T. cruzi infection, supporting that these are interconnected events." (PMID 25140115, 2014).